RNU6-1125P (RNA, U6 small nuclear 1125, pseudogene)
Gene: Small nuclear RNA gene on chromosome 7 (54,621,025 to 54,621,131, forward strand). Ensembl gene ENSG00000200471.
Homologues: Orthologues: chimpanzee U6 (100% identical), macaque U6 (91% identical), macaque U6 (89% identical). Paralogues in human: RNU6-480P (92% identical), RNU6-698P (89% identical), RNU6-890P (89% identical), RNU6-1309P (88% identical), RNU6-33P (88% identical), RNU6-38P (88% identical), RNU6-46P (88% identical), RNU6-742P (88% identical), RNU6-774P (88% identical), RNU6-86P (88% identical), RNU6-1 (87% identical), RNU6-1082P (87% identical), and 1283 more.